USP37 (ubiquitin specific peptidase 37)
Diseases named in the same sentence as USP37 in open-access papers (continued):
Sharing a sentence is not in itself a finding about the gene and the disease.
osteosarcoma (continued). "Our data analysis using TCGA and GTEx through GEPIA2 showed significant overexpression of USP37 in the osteosarcoma patients(n = 262) as compared to benign controls." (PMID 37118828, 2023). "In this study, we overexpressed USP37 in U2OS osteosarcoma cells and exposed them to replication stress induced by HU." (PMID 37118828, 2023). "After analyzing the TCGA data and observing elevated USP37 expression in the osteosarcoma cohort, we performed overexpression (OE) and knockdown (KD) experiments of USP37 using Myc-tagged USP37 plasmid, and si USP37 in the U2OS cell line." (PMID 37118828, 2023). "The KEGG and reactome pathway analysis showed that USP37 overexpression activates several distinct pathways in osteosarcoma cells, including Interferon signaling, Acute phase response signaling, Production of ROS, and HIF 1 alpha signaling." (PMID 37118828, 2023). "To further investigate the role of USP37 in cellular survival under replication stress in osteosarcoma cells, we inhibited USP37 using si-USP37 and exposed U2OS osteosarcoma cell line to HU-mediated replication stress (100 μM, 200 μM, 300 μM HU) for 24 h." (PMID 37118828, 2023). "Our study suggests that targeting USP37 can induce synthetic lethality in osteosarcoma by disrupting its oncogenic network and inducing replication stress." (PMID 37118828, 2023). "Depleting USP37 in osteosarcoma cells results in reduced recruitment to the replication fork, leading to instability of binding proteins, stalled replication fork, and enhanced apoptosis." (PMID 37118828, 2023). "RNA sequencing was utilized to assess the impact of USP37 overexpression and depletion on gene expression in osteosarcoma cells." (PMID 37118828, 2023). "Depletion of USP37 in osteosarcoma cells resulted in the accumulation of replication stress, as indicated by the spontaneous accumulation of γH2AX foci." (PMID 37118828, 2023). "We hypothesize that USP37 may be a potential contributor to poor prognosis in MYC-driven cancers such as osteosarcoma." (PMID 37118828, 2023). "We sought to investigate the effect of replication stress on USP37 in osteosarcoma cells." (PMID 37118828, 2023). "Interestingly, the study also showed that USP37 expression was low in normal bone marrow, while osteosarcoma tissue sections from patients who had undergone chemotherapy-induced alterations had elevated USP37 expression." (PMID 37118828, 2023). "To further analyze the dysregulated gene set in osteosarcoma cells after USP37 overexpression and knockdown, we used a ± 2 Log2 fold cut-off and identified a total of 349 genes dysregulated in the OE condition and 302 genes dysregulated in the KO condition compared to wild type." (PMID 37118828, 2023). "Furthermore, immunohistochemistry was performed on archived tissue blocks from osteosarcoma patients to establish a correlation between USP37 and PCNA expression." (PMID 37118828, 2023). "Understanding the oncogenic network of USP37 could lead to the development of new therapeutic modalities for osteosarcoma." (PMID 37118828, 2023). "Exposure of osteosarcoma cells to replication stress led to a further reduction in the number of replication tracts with co-labeling of both CldU and IdU, indicating that robust replication was compromised in response to replication stress in USP37-depleted cells." (PMID 37118828, 2023). "This suggests that USP37 may be involved in the progression of osteosarcoma." (PMID 37118828, 2023). "Various molecular assays, including colony formation, immunofluorescence, immunoprecipitation, and DNA replication restart, were employed to examine the physical interaction between USP37 and PCNA, as well as its physiological effects in osteosarcoma cells." (PMID 37118828, 2023). "To test the clinical relevance of our findings, we analyzed the co-expression of USP37 and PCNA in a retrospective cohort of 40 osteosarcoma patients." (PMID 37118828, 2023).
osteosarcoma (continued). "Our Kaplan -Meier curve analysis showed that osteosarcoma patients with high USP37 transcript levels have reduced OS and DFS as compared to a patient with low USP37 levels (Bii)." (PMID 37118828, 2023). "Since USP37 was found to interact with PCNA and our molecular docking data further corroborated this finding, the co-expression of PCNA was examined in the osteosarcoma tissue sections." (PMID 37118828, 2023). "Taken together, the immunohistochemistry study supports the findings from the in vitro and in silico experiments and suggests that USP37 and PCNA may play important roles in the progression of osteosarcoma." (PMID 37118828, 2023). "In vitro analysis showed that USP37 transcript and protein levels were significantly elevated in osteosarcoma cell lines U20S and MG63 compared to non-transformed cell line MCF 10A." (PMID 37118828, 2023). "Furthermore, we observed significant correlation of USP37 overexpression with overall survival (OS) and Disease Free Survival (DFS) in osteosarcoma patients (Bii)." (PMID 37118828, 2023). "The interaction between USP37 and PCNA is involved in the regulation of replication stress, and disrupting it could potentially trigger synthetic lethality in osteosarcoma." (PMID 37118828, 2023). "Our analysis revealed that USP37 levels were significantly higher in osteosarcoma tissues as compared to non-transformed tissue and that the expression of USP37 had a positive correlation with PCNA expression." (PMID 37118828, 2023). "Overall, our findings suggest that high expression or co-expression of USP37 and PCNA could be a predictor of therapeutic outcome in osteosarcoma patients." (PMID 37118828, 2023). "In continuation to our previous study, we have provided evidence here that USP37 interacts with PCNA, which is a critical protein in replication fork movement, by functioning as a sliding clamp loader, thereby regulating replication stress tolerance in osteosarcoma cells." (PMID 37118828, 2023).
thyroid cancer (2 papers, 2021 to 2025). "USP37 expression is downregulated in some cancers, such as kidney chromophobe and renal papillary cell carcinoma, prostate adenocarcinoma, renal adenocarcinoma, and thyroid carcinoma, paradoxically suggesting that USP37 may behave as a tumor suppressor." (PMID 34758854, 2021).
breast tumors (1 paper, 2018). "Currently, the underlying biological mechanism accounting for the elevated expression of USP37 in breast tumors remains unclear." (PMID 30482232, 2018).
glaucoma (1 paper, 2016). Increased pressure in the eyeball due to obstruction of the outflow of aqueous humor. "Four genes (CARD10, CWC27, RERE, and USP37) were nominally enriched (uncorrected P < 0.05) in the glaucoma cohort." (PMID 27896285, 2016).
glioma (1 paper, 2025). A benign or malignant brain and spinal cord tumor that arises from glial cells (astrocytes, oligodendrocytes, ependymal cells). "Specifically focusing on gliomas and considering the level of USP37 expression, we demonstrated its distribution in immune cells." (PMID 40926837, 2025). "This implies that USP37 might play a role in regulating the interactions between immune cells and tumor cells, potentially affecting glioma progression and immune evasion." (PMID 40926837, 2025).
invasive breast carcinoma (1 paper, 2021). A carcinoma that infiltrates the breast parenchyma. "The results achieved by bioinformatic analysis of invasive breast cancer data from TCGA suggested that knockdown of USP37 gene might interfere with cell cycle and chemoresistance to adriamycin." (PMID 33390801, 2021).
keloid (1 paper, 2025). An irregularly shaped, elevated mark on the skin caused by deposits of excessive amounts of collagen during wound healing. "Inhibition of USP37 or PI3K/AKT signaling attenuates these effects, highlighting the USP37/SALL4 axis as a critical regulator of keloid progression." (PMID 41424791, 2025). "USP37 promotes keloid pathogenesis by stabilizing SALL4 through deubiquitination, thereby sustaining PI3K/AKT activation and driving fibroblast growth, migration, invasion, glycolysis, and ECM accumulation." (PMID 41424791, 2025).
liver cancer (1 paper, 2025). An epithelial or non-epithelial malignant neoplasm that arises from the liver. "It has been reported that miR-30b-5p is significantly downregulated in liver cancer tissues and cell lines, where it mediates DNMT3A inhibition of proliferation and targets USP37 to slow the cell cycle." (PMID 40018039, 2025).
lung adenocarcinoma (1 paper, 2021). A carcinoma that arises from the lung and is characterized by the presence of malignant glandular epithelial cells. "Recently, hypomethylation of the USP37 promoter was found to be associated with its increased mRNA levels in lung adenocarcinoma and squamous cell carcinoma as well." (PMID 34758854, 2021). "We found that USP37 is considerably upregulated in many cancers, such as invasive breast carcinoma, cholangiocarcinoma, esophageal carcinoma, head and neck squamous cell carcinoma, hepatocellular liver carcinoma, lung adenocarcinoma, lung squamous cell carcinoma, and stomach adenocarcinoma." (PMID 34758854, 2021).
metastatic tumors (1 paper, 2025). "The expression of CENPN, STAT3 and USP37 in metastatic tumors from nude mice and human nasopharyngeal carcinoma tissues was verified by immunohistochemistry and immunofluorescence staining." (PMID 40458725, 2025). "In vivo studies demonstrated a reduced number of liver metastatic tumors in mice injected with CENPN knockdown cells, with decreased expression levels of CENPN, p-STAT3, and USP37." (PMID 40458725, 2025).
nasopharyngeal carcinoma (1 paper, 2025). A carcinoma arising from the nasopharyngeal epithelium. "CENPN directly binds to STAT3 and promotes STAT3 phosphorylation and nuclear translocation to regulate USP37 transcription, thus promoting the invasion and metastasis of nasopharyngeal carcinoma." (PMID 40458725, 2025). "The CENPN/STAT3/USP37 axis is expected to provide a new therapeutic target for nasopharyngeal carcinoma metastasis." (PMID 40458725, 2025). "Transcriptomic sequencing of shCENPN and shNC nasopharyngeal carcinoma cells revealed that USP37 expression was significantly reduced after CENPN knockdown." (PMID 40458725, 2025). "USP37 deubiquitinated the Snail protein to increase its stability, thus promoting the invasion and migration of nasopharyngeal carcinoma cells." (PMID 40458725, 2025). "CENPN is involved in the invasion and metastasis of nasopharyngeal carcinoma cells via USP37." (PMID 40458725, 2025). "The CENPN/STAT3/USP37 axis is expected to be a new target for nasopharyngeal carcinoma treatment." (PMID 40458725, 2025).
pancreatic cancer (1 paper, 2025). "USP37 was found to be aberrantly expressed in several tumor types, with significant association with poor prognosis in certain cancers, including pancreatic cancer." (PMID 40926837, 2025). "However, the role and underlying mechanisms of USP37 in pancreatic cancer remain unexplored." (PMID 40926837, 2025). "In this study, we found that USP37 plays a significant oncogenic role in pancreatic cancer, particularly in promoting cell proliferation and tumorigenesis." (PMID 40926837, 2025). "Functional assays demonstrated that USP37 fosters proliferation, migration, and invasion in pancreatic cancer cells, further underscoring its role as an oncogene." (PMID 40926837, 2025). "Critically, identifying specific substrates deubiquitinated by USP37 that drive pancreatic cancer pathogenesis represents a paramount focus for future investigation." (PMID 40926837, 2025). "This overexpression correlated with aggressive cell proliferation and increased tumorigenesis in murine models, underscoring USP37’s critical role in promoting malignancy in pancreatic cancer." (PMID 40926837, 2025). "To explore the role of USP37 in pancreatic cancer (PC) cell proliferation, we conducted a series of assays." (PMID 40926837, 2025). "USP37 protein levels were quantified via immunoblotting, and in vitro and in vivo functional assays were employed to assess its role in the proliferation of pancreatic cancer cells." (PMID 40926837, 2025). "Furthermore, we performed functional experiments with pancreatic cancer tissues and cells to elucidate the functions of USP37." (PMID 40926837, 2025). "Additionally, Western blotting was conducted to evaluate USP37 expression in clinical samples and pancreatic cancer cell lines." (PMID 40926837, 2025). "We found correlations between USP37 expression and key immune modulators, suggesting that it might contribute to immune evasion, which is a known feature of pancreatic cancer’s poor immunogenicity." (PMID 40926837, 2025). "The evidence suggests that targeting USP37 could provide a promising strategy for curbing pancreatic tumor growth." (PMID 40926837, 2025). "The consistent overexpression of USP37 in PAAD tumors and cell lines, as well as its differential expression across various pancreatic cancer cell lines, underscores its potential as a key regulator in PC development." (PMID 40926837, 2025). "Additionally, while USP37 has been identified as a potential therapeutic target due to its role in tumor growth, its therapeutic applicability in pancreatic cancer has not yet been validated in preclinical models." (PMID 40926837, 2025). "Collectively, our results highlight the oncogenic role of USP37 in PAAD and suggest that targeting the USP37 pathway could serve as a potential therapeutic approach to suppress tumor growth and improve immune responses in pancreatic cancer." (PMID 40926837, 2025).
viral infection (1 paper, 2025). "The results showed that SIVmac239-WT-GFP virus infection decreased the expression of SAMHD1 in the USP37 knockdown group when compared to that in the control group." (PMID 39655951, 2025). "Given that HIV-2/SIV Vpx hijacks the CRL4 (DCAF1) E3 ubiquitin ligase complex to degrade SAMHD1, thereby promoting viral infection, we investigated whether USP37 reverses SIVmac239 Vpx-mediated SAMHD1 degradation." (PMID 39655951, 2025).
cancer (21 papers, 2014 to 2026). A tumor composed of atypical neoplastic, often pleomorphic cells that invade other tissues. "Gene Set Enrichment Analysis (GSEA) was performed to identify cancer hallmarks associated with USP37." (PMID 40926837, 2025). "Mechanistically, USP37 is implicated in key cancer pathways, likely through epigenetic regulation, as evidenced by DNA methylation analyses and gene set enrichment findings." (PMID 40926837, 2025). "These curves demonstrated a clear association between elevated USP37 levels and worse patient outcomes in these cancer types." (PMID 40926837, 2025). "In this study, we mainly conducted a comprehensive pan-cancer analysis of USP37 in expression levels, mutation status, patient prognosis, and immune infiltration using public databases." (PMID 40926837, 2025). "Significantly, while our findings and existing literature establish USP37 as a promoter of tumorigenesis and metastasis in cancers like LIHC, its association with favorable prognosis in KIRC presents a compelling tissue-specific paradox." (PMID 40926837, 2025). "Overall, these findings highlight a robust association between USP37 expression and immune infiltration levels in these cancers." (PMID 40926837, 2025). "Recent studies reported that USP37 was associated with the regulation of cell proliferation in cancers." (PMID 26427597, 2015). "The investigation covered gene expression differences among different cancers, examined the relationship between USP37 expression and patient survival, explored its mutation profile, and assessed its link to immune infiltration and key cellular signaling pathways." (PMID 40926837, 2025). "These advances implicated that USP37 gene may be associated with the stemness of tumor cells facilitating cancer progression." (PMID 30482232, 2018). "USP37 holds promise as a biomarker and therapeutic target in clinical oncology, providing new insights into its function in cancer." (PMID 40926837, 2025). "Accordingly, there is a need for additional investigations to uncover the USP37 regulatory functions and molecular mechanisms in a comprehensive cancer dataset." (PMID 40926837, 2025). "By integrating these analyses, the study seeks to clarify USP37’s biological functions in cancer progression and its potential as a therapeutic target and prognostic marker." (PMID 40926837, 2025). "Although its involvement in cancer development is well-established, the comprehensive pan-cancer analysis of USP37 remains relatively uncharted." (PMID 40926837, 2025). "The results indicated that USP37 was significantly associated with at least one of the four methyltransferase genes (DNMT1, DNMT2, DNMT3A, and DNMT3B) in various cancer types, except UCS." (PMID 40926837, 2025). "This study conducted a systematic analysis of USP37 across various cancer types using several public databases, including TCGA, to investigate its potential role in tumor development and prognosis." (PMID 40926837, 2025). "The prognostic relevance of USP37 across various cancers was analyzed using univariate Cox regression and Kaplan–Meier survival curves." (PMID 40926837, 2025). "Based on these, our study suggests USP37 as a novel biomarker to predict prognosis and immune therapy response in diverse cancer types." (PMID 40926837, 2025). "Our analysis revealed that USP37 exhibits a strong positive correlation with most immune regulators in cancers such as HNSC, KIRC, LIHC, PRAD, and READ while showing a strong negative correlation with most immune regulators in SARC." (PMID 40926837, 2025). "In particular, the DUB USP37 has been linked to the DNA damage response (DDR), genome stability and DNA replication, and its overexpression provides a survival advantage to cancer cells." (PMID 40533495, 2025).